MMP14 (matrix metallopeptidase 14)
Diseases named in the same sentence as MMP14 in open-access papers (continued):
Sharing a sentence is not in itself a finding about the gene and the disease.
cervical carcinoma (28 papers, 2009 to 2026). A carcinoma arising from either the exocervical squamous epithelium or the endocervical glandular epithelium. "MMP14 polymorphisms influence cancer susceptibility and clinical characteristics, including that of cervical cancer, esophageal squamous cell carcinoma, and HCC." (PMID 34007838, 2021). "More importantly, CCAT1 can promote cervical cancer cell proliferation and invasion by regulating the miR-181a-5p/MMP14 axis." (PMID 36313765, 2022). "Studies have shown that MMP14 is involved in the progression of cervical cancer (CC) by promoting angiogenesis, invasion, and lymph node metastasis, and it has also been reported that MMP14 overexpression is associated with poor prognosis of cervical cancer." (PMID 34604053, 2021). "CCAT1 promotes the proliferation and invasion of cervical cancer cells via the miR-181a-5p/MMP14 axis and promotes endometrial carcinoma via miR-181a-5p." (PMID 33193573, 2020). "To date, several studies have verified LUCAT1/miR-181a axis, miR-181a-5p/TGFβI axis and miR-181a-5p/MMP14 axis in cervical cancer." (PMID 32849815, 2020). "CCAT1 plays a role in promoting the proliferation and invasion of cervical cancer by regulating the miR-181a-5p/MMP14 axis and promotes endometrial carcinoma progression by miR-181a-5p." (PMID 33193573, 2020). "The high expression of MMP-14 described by Zhai and colleagues in tissues of cervical carcinomas corresponds to our finding of strong mRNA expression in Caski and SiHa cell lines." (PMID 20942921, 2010). "This study aimed to assess whether the expression of MMP-2, MMP-9, MMP-14, TIMP-1, and TIMP-2 in tumors and in the adjacent stroma is associated with cervical cancer prognosis." (PMID 32669083, 2020). "For instance, silencing of miR-484 could aggravate the malignancy of cervical cancer cells by inhibiting MMP14 and HNF1A." (PMID 32232409, 2020). "MMP-14 was also detected in the cervix-carcinoma cell lines Caski and SiHa." (PMID 20942921, 2010). "The results further demonstrated that MMP14 and HNF1A were upregulated in cervical cancer tissues compared with the normal cervix." (PMID 31810492, 2019). "To further explore the expression levels of MMP14 and HNF1A in cervical cancer, we performed RT-qPCR analyses to examine their expression levels in 20 pairs of CC tissues and adjacent non-tumor tissues as well as a panel of cervical cancer cell lines." (PMID 31810492, 2019). "Collectively, the present work provides the first evidence of the coordination of methylation modulated miR-484 and MMP14/HNF1A in the regulation of the cell adhesion, EMT, and the β1-integrin pathway during cervical cancer carcinogenesis." (PMID 31810492, 2019). "Further analysis revealed that MMP14, 23B and 25 were located in significant genomic amplification regions and MMP1, 15, 17 and TIMP1 in all our 6 cervical cancer cell lines." (PMID 29312578, 2017). "This TGF-β1 is then processed by either the epithelial cell specific integrin ανβ6 or by MMPs, especially active MMP-2 in complex with MMP-14 and TIMP-2 on the cell membrane of cervical cancer cells at the epithelial cell–stroma border." (PMID 19352388, 2009). "Furthermore, upregulation of both matrix metalloproteinase 14 (MMP14) and HNF1A was reported to promote cell motility and metastasis through induction of epithelial-mesenchymal transition (EMT) in cervical cancer cells." (PMID 41583511, 2026). "At the same time, silencing miR-484 can be down HNF1A/MMP14 and inhibited the growth and metastasis of tumor cells, on the other hand, the overexpression of HNF1A/MMP14 promoted the adhesion and EMT process in cervical cancer." (PMID 34234870, 2021). "Meanwhile, ectopic expression of miR-337-3p repressed the promoter activity and transcription of MMP-14 in cervical cancer HeLa cells, but not in renal cell carcinoma 786-O cells." (PMID 26084291, 2015).
cervical carcinoma (continued). "It was established that in cervical cancer tissue, the immunohistochemical expression of MMP-14 was greatly increased, while in normal tissues of the endometrium and myometrium, the expression of MMP-14 was absent or insignificant." (PMID 34830452, 2021).
breast tumor (26 papers, 2006 to 2023). "Together with the data demonstrating co-IP of CAIX with these proteins, the observations of colocalization suggest that the association of CAIX with integrins and MMP14 play a potential role in the regulation of breast tumor cell migration." (PMID 28692057, 2017). "Overall, our study builds on a recent study of mouse tumors engrafted in nude mice, and shows that MMP-14 blockade within breast tumors and TME limits tumor progression and metastasis." (PMID 28938563, 2017). "In datasets of primary breast tumors, high expression levels of a subset of MMPs, including MMP7 and MMP14, are correlated to poor prognosis and decreased survival rates." (PMID 35719919, 2022). "Studies showed that the expression of PROX-1 in breast tumor cells could reduce the MMP14-dependent invasiveness of the tumor cells, and PROX-1 may be a suppressor gene in breast tumor cells." (PMID 35054174, 2021).
atherosclerosis (25 papers, 2013 to 2025). A disease characterized by the build-up of fatty material and calcium deposition in the arterial wall resulting in partial or complete occlusion of the arterial lumen. "These ARF6-mediated events lead to activation of MMP14, a membrane-bound collagenase upregulated in atherosclerosis." (PMID 35680971, 2022). "MMP-14 or membrane type-I matrix metalloproteinase (MT1-MMP) regulates the development of atherosclerosis, by promoting the cleavage of LDL receptor." (PMID 36553147, 2022). "Metalloproteinases (MMPs), such as Mmp14, play an important role in the pathogenesis of atherosclerosis by participating in vascular remodeling, smooth muscle cell migration, and plaque disruption." (PMID 35350534, 2022). "High levels of MMP-14 were associated with CVD, which is in line with previous research showing that MMP-14 is involved in the development of atherosclerosis with consequent cardiovascular disease." (PMID 34702365, 2021). "Our data demonstrate that TIMP-2 plays a greater protective role than TIMP-1 during the pathogenesis of atherosclerosis, in part by suppressing MMP-14-dependent monocyte/macrophage accumulation into plaques." (PMID 26645981, 2016). "MMP14 can be relevant to unstable atherosclerosis, and emphysematous lungs exhibit an upregulation of MMP14 in alveolar macrophages." (PMID 27801806, 2016). "Our findings indicate that MMP-14 is a pertinent therapeutic target for the prevention of clinical atherosclerosis and other inflammatory diseases." (PMID 26645981, 2016). "In the present study, we found that MMP-14 is negatively correlated with angiogenesis at the advanced stages of atherosclerosis in rabbits." (PMID 25233229, 2014). "Matrix metalloproteinase-14 (MMP-14) is involved in the development of atherosclerosis and CVD." (PMID 34702365, 2021). "To corroborate and relate our findings to atherosclerosis, we investigated whether nullifying MMP-14 impedes monocyte recruitment into plaques." (PMID 26645981, 2016). "Upregulation of MMP-1, -2, -3, and -9 and downregulation of MMP-14 may contribute to intraplaque angiogenesis and plaque instability at the advanced stage of atherosclerosis in rabbits." (PMID 25233229, 2014). "In conclusion, as shown in this rabbit model of atherosclerosis, upregulation of MMP-1, -2, -3, and -9 and downregulation of MMP-14 may participate in intraplaque angiogenesis at the advanced stages of atherosclerosis." (PMID 25233229, 2014). "Therefore, downregulation of MMP-14 may participate in intraplaque angiogenesis at the advanced stages of atherosclerosis." (PMID 25233229, 2014). "Proteins that play a role in the progression of atherosclerosis such as PAI-1 and MMP-14 were also elevated in AMPKα1 KO macrophages." (PMID 36586434, 2023). "The most important finding in this study is that in this rabbit model of atherosclerosis, MMP-1, -2, -3, and -9 were positively correlated and MMP-14 was negatively correlated with intraplaque angiogenesis at the advanced stages of atherosclerosis." (PMID 25233229, 2014). "Changes in concentrations of MMP-9 and MMP-14 were found in both investigated CAD groups, with MMP-9 levels being significantly higher in obstructive CAD samples than in INOCA/ANOCA, which confirms the role of inflammation in the development of atherosclerosis." (PMID 39684689, 2024). "The increased expression of genes related to ECM degradation (e.g., Mmp14 and Adamts4) is consistent with previous findings showing that glucose-induced advanced glycation end products (RAGE) mediate modification of the components of the ECM and accelerate atherosclerosis under diabetic conditions." (PMID 35350534, 2022). "We present novel data showing that TIMP-2 but not TIMP-1 acts as an important modulator of the MMP-14-directed monocyte/macrophage invasion that reduces accumulation in atherosclerotic lesions in vivo and therefore plays a protective role during the pathogenesis of atherosclerosis." (PMID 26645981, 2016).
colon carcinoma (25 papers, 2004 to 2025). "Immunofluorescence was utilized to demonstrate MMP14 expression in colon cancer tissues, while Hematoxylin and eosin (HE) staining was employed to observe the histology of normal tissue and colon cancer tissue." (PMID 40352589, 2025). "In this study, we examined the augmented levels of MMP14 expression in colon tumor tissues compared to normal tissues." (PMID 40352589, 2025). "Secreted MMP-14 levels and their changes after regorafenib treatment in human colon cancer cell line were assessed, in which the secreted MMP-14 concentration was normalized by cell number and indicated." (PMID 39199626, 2024). "It was also indicated that in aggressive human breast and colon cancer, miR-181a-5p was significantly downregulated, and its levels were inversely correlated with the expression of MMP-14." (PMID 39062015, 2024). "Recent work revealed that MMP14 overexpression via knockdown of its repressor potentiated tumor desmoplasia and chemoresistance in colon cancer." (PMID 35223528, 2022). "Our findings suggest that HES1 regulate MMP14 expression through up-regulating STAT3 activity in colon cancer cells." (PMID 26650241, 2015). "Among the genes, which are consistently promoter-hypomethylated in both mice and humans (54 genes), we identified the matrix metalloproteinase and colon cancer prognostic marker Mmp14, which is also over-expressed in mouse adenoma." (PMID 23408899, 2013). "Research before had indicated that miR-181a could restrain migration and carcinogenesis of breast and colon cancer cells by down-regulating MMP-14." (PMID 34374662, 2021). "Furthermore, inhibition of MMP-14 and tumor angiogenesis in two murine sarcoma and colon carcinoma models has been reported for the green tea ingredient (−)-epigallocatechin gallate (EGCG)." (PMID 29112161, 2017). "We therefore evaluated whether STAT3 activity plays a role in HES1’s regulation of MMP14 in colon cancer cells." (PMID 26650241, 2015). "It has been observed that hypoxia-induced upregulation of MMP2 and MMP9 in breast and colon cancer cells contributed to tumor cell invasion and a membrane-bound form of MMP—MT1-MMP (MMP-14) is also induced via hypoxia in breast and renal carcinoma cells." (PMID 30356678, 2018). "The expression of MT1-MMP and MMP-14 is elevated in tumours of the colon and has been described as a target of the Wnt pathway MMP-2 is related to tumour invasion and it has been demonstrated that there is a greater expression of its transcription on the invasive front of the colon tumour." (PMID 25932044, 2015).
osteosarcoma (24 papers, 2009 to 2026). A usually aggressive malignant bone-forming mesenchymal neoplasm, predominantly affecting adolescents and young adults. "MMP-2, MMP-7, MMP-9, and MMP-14 have been linked to the progression and metastasis of osteosarcoma." (PMID 38816365, 2024). "Our study suggested that MELTF-AS1 functioned as a pro-metastasis gene in osteosarcoma by upregulating MMP14 and that it could be a potential therapeutic and diagnostic target for osteosarcoma." (PMID 34729248, 2021). "De-localization of claudin-1 from tight junctions has been observed in metastatic osteosarcoma cells, suggesting its involvement in metastasis could be linked to MMP14 activity." (PMID 31466240, 2019). "In addition, the destruction of bone tissue caused by osteosarcoma invasion is regulated by MMP14 activity together with the endocytic collagen receptor uPARAP/Endo180 in osteosarcoma cells, a process that, contrary to bone metastases of epithelial cancers, does not require osteoclast activity." (PMID 31466240, 2019). "MMP13, MMP2, and MMP14 have been identified to interact with each other and to promote the progression and invasion of osteosarcoma." (PMID 38966281, 2024). "For instance, WNT5A promotes MMP‐14 expression and cell motility in human osteosarcoma cells via the ERK pathway." (PMID 39466654, 2024). "Further, three previously identified potential gene targets of ACT for osteosarcoma, including CADM1, CDH11, and MMP14, also showed high protein expression in osteosarcoma compared with normal adjacent tissues." (PMID 37457661, 2023). "The mRNA levels for metalloproteinases, MMP-7 and MMP-14, were significantly increased in all analysed osteosarcoma cells compared to the HeLa cell line and hASCs." (PMID 36139691, 2022). "The results confirmed the molecular phenotype of the osteosarcoma cells, associated with their invasiveness and manifested by low expression of MEG3 and high mRNA levels for metalloproteinases, especially for MMP-14." (PMID 36139691, 2022). "qRT-PCR results showed that the RNA level of MMP14 decreased after MELTF-AS1 was silenced in osteosarcoma cells, and the decreased MMP14 returned to normal level when silencing MELTF-AS1 was combined with transfection of miR-485-5p inhibitors." (PMID 34729248, 2021). "Osteosarcoma cells express high levels of MMP14 mRNA, and the corresponding protein correlates with poor prognosis in patients." (PMID 31466240, 2019). "The comparison of the gene expression between osteosarcoma samples and matching normal bone tissue also reveals MMP14 as one of the most significantly upregulated genes." (PMID 31466240, 2019). "In rhabdomyosarcoma, furin expression has been linked to malignancy in part due to its function in the processing of pro-MMP14, whereas in osteosarcoma, furin inhibition leads to reduced MMP14-dependent cell migration." (PMID 31466240, 2019). "Other studies, however, have shown that colchicine treatment can influence MMP-2 activity and MMP-14 gene expression in osteosarcoma cells." (PMID 30931350, 2017). "Thus, in this study, we determined the expression of metalloproteinases, i.e., MMP-7 and MMP-14 involved in paediatric tumour pathogenesis, including osteosarcoma." (PMID 36139691, 2022). "Furthermore, lncRNA MELTF-AS1 regulated the expression of MMP14 and enhanced osteosarcoma metastasis." (PMID 35992869, 2022). "MELTF-AS1 can enhance the metastatic ability of osteosarcoma cells by regulating MMP14 expression." (PMID 34729248, 2021). "Here, we found that MELTF-AS1 competed with MMP14, a key pro-metastasis gene, for miR-485-5p and relieved the inhibitory effect of miR-485-5p on MMP14, thereby leading to increased MMP14 expression and metastasis ability of osteosarcoma cells." (PMID 34729248, 2021). "However, MMP14-targeting microRNAs, such as miR-193a-3p and miR-133a inhibit osteosarcoma proliferation, invasion, and metastasis." (PMID 31466240, 2019).
osteosarcoma (continued). "Moreover, it was revealed that mRNA levels for MMP-14 differ significantly among the tested OS cell lines, suggesting that it may be an important marker of osteosarcoma development." (PMID 36139691, 2022). "In addition, overexpression of MELTF-AS1 in osteosarcoma cells could lead to increased expression of MMP14, but if overexpression of MELTF-AS1 was accompanied by overexpression of miR-485-5p, the increase of MMP14 was weakened." (PMID 34729248, 2021). "Thus, the MELTF-AS1/miR-485-5p1/MMP14 axis may provide a novel therapeutic target for osteosarcoma treatment." (PMID 34729248, 2021). "Evaluated osteosarcoma cell lines showed characteristic phenotypes with unique patterns related to upregulation of MMP-7, MMP-14, BMP-7, miR-21-5p, miR-124-3p and downregulation of lncRNA MEG3." (PMID 36139691, 2022). "Correlation analysis in osteosarcoma tissues indicated that the expression of miR-485-5p was negatively correlated with the expression of MELTF-AS1 and MMP14, while the expression of MELTF-AS1 was positively correlated with the expression of MMP14." (PMID 34729248, 2021). "By modulating MMP14 expression, the lncRNA MELTF-AS1 may enhance osteosarcoma metastasis." (PMID 35178091, 2022). "In addition, RNA level of MMP14 was elevated in osteosarcoma tissues, and it was higher in osteosarcoma tissues with distant metastasis than in non-metastatic osteosarcoma tissues." (PMID 34729248, 2021). "Moreover, a dominant-negative soluble LPR5 reduces the expression of MMP-2 and MMP-14, consistent with a decrease in invasive properties of the human SaOS2 osteosarcoma cell line." (PMID 31370265, 2019).